DSCAM-AS1 (DSCAM antisense RNA 1)
Diseases named in the same sentence as DSCAM-AS1 in open-access papers (continued):
Sharing a sentence is not in itself a finding about the gene and the disease.
cancer (14 papers, 2016 to 2025). A tumor composed of atypical neoplastic, often pleomorphic cells that invade other tissues. "Further studies demonstrated overexpression of DSCAM-AS1 in various other cancer entities, always being associated with poor survival, like in non-small cell lung cancer, colorectal cancer, osteosarcoma, hepatocellular carcinoma and melanoma." (PMID 35885035, 2022). "DSCAM-AS1 positively correlated genes were significantly associated with clinical signatures associated with increased cancer aggression, tamoxifen resistance, higher grade, stage and metastasis." (PMID 27666543, 2016). "Since the aberrant expression of genes in cancers is usually caused by copy number variations (CNVs), epigenetic and transcriptional dysregulations, we firstly analyzed the CNVs status at the gene body of DSCAM-AS1." (PMID 32929382, 2020). "In these cancers, DSCAM‐AS1 modulates the expression of FOXA1 and ERα by interacting with YBX1, influencing YBX1 recruitment to the promoter regions of FOXA1 and Erα and thereby promoting tumour progression." (PMID 39690143, 2024). "DSCAM-AS1 has been reported to act as an oncogene in other cancer types and the aim of our study was to uncover the function and regulatory mechanism of DSCAM-AS1 in CC." (PMID 31737900, 2020). "DSCAM-AS1 expression is elevated specifically in indicated types of human cancers, BRCA, LUAD, and PRAD, which shows that DSCAM-AS1 functions as an oncogenic molecule." (PMID 32929382, 2020). "Studies show that DSCAM-AS1 has a role in progression of several cancers, and that it can function as an oncogenic lncRNA in these cancers." (PMID 32453706, 2020). "Kyoto Encyclopedia of Genes and Genomes (KEGG) pathway analysis revealed that DSCAM‐AS1 was highly correlated with DNA replication, cell cycle, pyrimidine metabolism, mismatch repair and other cancer‐related pathways." (PMID 30430768, 2018). "Together, these results highlight the crucial role of DSCAM‐AS1 in cell cycle and cancer progression." (PMID 30430768, 2018). "To further characterize the impact of DSCAM-AS1 on cancer phenotype, we performed a mouse xenograft tumour growth assay, showing that loss of DSCAM-AS1 reduces the growth of implanted T47D cells in vivo." (PMID 27666543, 2016). "High levels of DSCAM-AS1 were observed only in overt carcinoma tissues, while it is almost undetectable in either the adjacent normal tissues or pre-neoplastic lesions." (PMID 26621851, 2016). "FOXA1 binds directly to the promoter of DSCAM‐AS1, modulating its expression in cancer cells." (PMID 39690143, 2024). "Notably, among the genes downregulated upon DSCAM-AS1 knockdown were several proliferation activators of endometrial (and other) cancer cells, like NOTCH1, HMGA2, PTK2/FAK, FOSL1, GREM1 and EGR1." (PMID 35885035, 2022). "Thus, DSCAM-AS1 represents an important therapeutic target in cancers being capable of affecting several cancer-related mechanisms." (PMID 34708048, 2021). "We failed to build a homozygous DSCAM-AS1-deletion cells, which might be due to the fact that DSCAM-AS1 is vital for cancer cell growth." (PMID 32929382, 2020). "The relevance of DSCAM-AS1 overexpression in BC is confirmed by clinical data and further enhanced by its possible involvement in the regulation of RNA processing, which is emerging as one of the most important dysfunctions in cancer." (PMID 32503257, 2020). "Furthermore, DSCAM‐AS1 (DSCAM Antisense RNA 1) has been found to play carcinogenic roles in different types of cancer and could promote the progression of PCA by interacting with YBX1." (PMID 40259205, 2025). "However, high expression of DSCAM-AS1 and many genes positively correlated with DSCAM-AS1 have been consistently associated with poor clinical outcomes, such as cancer aggression, tamoxifen resistance, higher grade, stage, and metastasis in ER-positive and luminal BC types." (PMID 32716908, 2020).
cancer (continued). "Our study revealed that the lineage-specific expression of DSCAM-AS1 was regulated by the FOXA1-driven super-enhancers (SEs) and DSCAM-AS1 can regulate expression of FOXA1 and ERα to maintain the characteristics of indicated cancer cells." (PMID 32929382, 2020).
tumor (13 papers, 2016 to 2024). "In the Luminal B subtype, overexpression of DSCAM-AS1, has been previously reported to mediate tumor progression and tamoxifen resistance." (PMID 32753692, 2020). "The only reported protein that directly interacts with DSCAM‐AS1 is hnRNPL, which mainly exists in the cytoplasm to promote tumor invasion." (PMID 30430768, 2018). "We demonstrate that DSCAM-AS1 mediates tumour progression and tamoxifen resistance and identify hnRNPL as an interacting protein involved in the mechanism of DSCAM-AS1 action." (PMID 27666543, 2016). "Remarkably, over-expression of DSCAM-AS1 in these samples has been correlated with tumor relapse." (PMID 34708048, 2021). "We demonstrated DSCAM-AS1 depletion has profound effects on growth of MCF7 xenograft tumor." (PMID 32929382, 2020). "For example, What is the detailed function of DSCAM‐AS1 in tumor progression?" (PMID 30430768, 2018). "Thus, our data suggest that DSCAM-AS1 might also have a tumor-promoting role in endometrial carcinogenesis via activation of sciellin." (PMID 35885035, 2022). "Compared to negative control cells, the DSCAM-AS1 knockout cells showed a significant lower tumor formation rate." (PMID 32929382, 2020).
DSCAM-AS1 also shares sentences with these, for which no sentence is quoted: melanoma (2 papers); bone metastasis (1); Endometrial Adenocarcinoma (1); endometrioid endometrial adenocarcinoma (1); hepatocellular carcinoma (1); infection (1); lymph node metastasis (1); non-small cell lung carcinoma (1); osteosarcoma (1); viral infection (1).